CXCR3 (C-X-C motif chemokine receptor 3)
Diseases named in the same sentence as CXCR3 in open-access papers (continued):
Sharing a sentence is not in itself a finding about the gene and the disease.
colitis (continued). "To address this issue, we deleted CXCR3 from the CD25−/− mice, which resulted in aggravated cholangitis but alleviated colitis." (PMID 29868034, 2018). "For the alleviated colitis in the CD25−/−CXCR3−/− mice, our findings were in agreement with previous report for CXCR3 being a colon-specific T cell homing receptor." (PMID 29868034, 2018). "In particular, CXCL10 has received considerable attention in recent years and has been shown to be upregulated during colitis, while CD tissues have been shown to express another ligand, CXCL9, as well as CXCR3." (PMID 29707158, 2018). "We have shown that CXCL10 blockade ameliorates spontaneous experimental colitis, which is mediated predominantly by Th1-type αb TCR+ CXCR3+ cells." (PMID 29707158, 2018). "In particular, deletion of CXCR3 in CD25−/− mice lead to opposite results in cholangitis and colitis and increased percentage of hepatic PD-1+ cells." (PMID 29868034, 2018). "In the current study, we detected a significantly higher colonic expression of Ccl2, Cxcl1, Cxcl2, and Cxcr3 genes in the control and RB groups (p < 0.05, RB vs. control) compared to the FRB group, which supports the protective effect of FRB in colitis." (PMID 28703759, 2017). "To date, targeting of chemokine receptors such as CCR2, CCR5, CCR6, CXCR3, CXCR4 and CX3CR1 by gene disruption or antagonistic peptides has been found to protect animals from DSS colitis." (PMID 21283540, 2011). "CXCL10 and its receptor CXCR3 have been shown to be upregulated in IL-10 knockout (IL-10−/−) mice and those with dextran sulphate sodium (DSS)-induced colitis." (PMID 20360984, 2010). "In contrast, we noticed a modest decrease in the number of PP CXCR3+, IFN-γ+, CXCL9+ and CXCL11+ NK cells during live Mycobacteria-enhanced colitis." (PMID 18533024, 2008). "We also examined its effect on the intricate network of cytokines, chemokines, and transcription factors involved in chronic inflammation and colitis, including TNF-α, IL-6, IFN-γ, IL-1β, C-X-C motif chemokine receptor 3 (CXCR3), signal transducer and activator of transcription (STAT3), NF-κB." (PMID 39255739, 2024). "Importantly, increased Th1 cells within the colon is consistent with recent findings where CXCR3 and its ligands CXCL10/CXCL9 were shown to be enhanced within the colon during immunotherapy-induced colitis." (PMID 36173679, 2022). "In colon, considering the low frequency of CD4+ Tcm cells in CD25−/− mice and unchanged PD-1 expression on CD4+ T cells after CXCR3 deletion, we proposed that the reduced migration of PD-1+ CD4+ T cells into the colon is primarily responsible for alleviated colitis." (PMID 29868034, 2018). "CXCR3 interactions with CXCL9, CXCL10 and CXCL11 are important for the selective homing of Th1 effectors cells, which mediate mucosal immunity, inflammation, and colitis." (PMID 18533024, 2008). "Although other tissues such as the gut epithelium also express CXCR3 chemokines, and comparatively small increases in PTPN2‐deficient CAR T cells were detected in the colon (lamina propria), this was not accompanied by overt tissue damage or colitis." (PMID 31803974, 2020). "Taken together, our results suggest that the role of CXCR3 in cholangitis is not mediated by its chemotaxis function, whereas CXCR3-mediated T cell homing to the gut could be a factor for the colitis of CD25−/− mice." (PMID 29868034, 2018). "Taken together, these data show that in the absence of CXCR3, the migration of CD4+ T cells and neutrophils to the colon is impaired during colitis." (PMID 24992040, 2014). "While neither NK nor NKT cell subsets largely expressed CXCR3, there were substantially more CXCL10+ NK cells in the MLN, PP, and LP during Mycobacteria-enhanced colitis, than compared to other groups." (PMID 18533024, 2008).
glioma (28 papers, 2014 to 2025). A benign or malignant brain and spinal cord tumor that arises from glial cells (astrocytes, oligodendrocytes, ependymal cells). "This duality makes CXCR3 as an effective target for glioma, and so the underlying mechanisms need to be further explored to identify suitable specific targets from its downstream pathway." (PMID 39429695, 2024). "To validate this idea, we compared the antitumor efficacy of T-αFGL2 in treating glioma-bearing wild-type (WT) mice and CXCR3-deficient (CXCR3-/-) mice." (PMID 36759517, 2023). "The expression of CXCR3 is elevated in glioma cells and is associated with tumor malignancy." (PMID 40786052, 2025). "In addition, we suggest here that NFATc3 is a key positive regulator of RCAN1-4, COX-2; TNF-α; CXCR-3, GM-CSF and IL-2, known to be implicated in glioma growth." (PMID 31249342, 2019). "In the context of glioma immunotherapy, the prevailing consensus is that activation of the CXCR3 pathway can enhance peritumoral T-cell infiltration and subsequently exert tumor-suppressive effects." (PMID 39429695, 2024). "Previous research has indicated that CXCR3 contributes to glioma invasiveness, tumor immune responses, and antitumor drug treatments." (PMID 39429695, 2024). "Gliomas originate from glial cells, and CXCR3 and its ligands are widely expressed in various glial cells." (PMID 39429695, 2024). "Glioma cells also express CXCR3, regulated by pathways like COX-2/NF-κB and LRP1-mediated internalization, which enhance tumor invasiveness and aggressiveness through ERK1/2 phosphorylation and calcium channel activation." (PMID 39429695, 2024). "Intriguingly, the T-αFGL2 treatment increased CXCR3 expression on CD69+CD8+ TM cells in glioma-bearing brains compared with T-Ctr treatment." (PMID 36759517, 2023). "CXCL10 activated CXCR3+ effector T cells, which stimulated T cells to release more CXCL10, further enhancing the chemoattraction of CXCR3+ T lymphocytes and antigen-specific cytotoxic T lymphocytes to gliomas." (PMID 38104126, 2023). "CXCL10 showed tumor-promoting properties and the manifestation of chemokine receptor/ligand pair CXCR3/CXCL10 had an essential role in the proliferation of glioma." (PMID 36091778, 2022). "A previous study suggested that the expression of chemokine receptor/ligand pairs such as CXCR3/CXCL10 plays an important role in the proliferation of glioma cells." (PMID 32943658, 2020). "On the other hand, in the mouse glioma model, the high protein and mRNA level of Ccl2, Cxcl10 and Cxcr3 were decreased by celecoxib." (PMID 32943658, 2020). "Combining the results obtained by silencing or over-expressing NFATc3, this study indicates that this member is involved in RCAN1-4, COX-2, TNF-α, IL-2, GM-CSF and CXCR-3 gene regulation in U251 glioma cells." (PMID 31249342, 2019). "The CXCL10/CXCR-3 axis has been shown to be expressed in glioma cells, and NFATc3 dependent regulation of CXCR3 is on line with the role of this receptor in migration and site specific dissemination in many cancerous cells." (PMID 31249342, 2019). "The functional role of CXCR3-A was studied in U87 glioma cells overexpressing CXCR3-A, in glioma cells that endogenously express high levels of CXCR3 and in cells from glioblastoma patients." (PMID 29146996, 2017). "We used the U87 glioma cell line in the subsequent studies since it expresses low CXCR3 levels and can, therefore, be engineered with adequate expression vectors." (PMID 29146996, 2017). "Stimulation of CXCR3-positive glioma cells with the agonist led to a marked increase in calcium flux and in phospho-Erk1 and phospho-Erk2." (PMID 29146996, 2017). "A recent study demonstrates that CXCL10 and its receptor, CXCR3, are upregulated in human glioma cells." (PMID 26506595, 2016). "CXCR3 antagonists have been shown to inhibit glioma growth and prolong survival." (PMID 40786052, 2025). "This situation makes it crucial to pay attention to the role of CXCR3 and its ligands in glioma." (PMID 39429695, 2024).
glioma (continued). "CXCR3 and its ligands play important roles in the invasion and migration of glioma." (PMID 39429695, 2024). "Pharmacological inhibition of Cxcr3 in murine malignant glioma (GL261) model showed antitumor progression effect, suggesting the connection between CXCR3 and glioma progression and CXCR3 could be a potential therapeutic target for glioma." (PMID 35794867, 2022). "Endogenous CXCR3 protein levels measured in all glioma cell lines by immunoblotting were variable." (PMID 29146996, 2017). "We observed that the expression of apoptosis-related factors (cleaved caspase 3 and Bad) was lower, while the expression of anti-apoptosis (Bcl2), invasion (MMP2 and MMP9) and chemokine pathway related factors (CXCL10 and CXCR3) was higher in glioma tissues than in normal tissues." (PMID 26506595, 2016). "Interestingly, IP10 is required for CNS glioma homing as well as the induction of effector CTLs because its receptor, CXCR3, is highly expressed on active T cells." (PMID 24816916, 2014). "This increased the infiltration of CD8+ T cells (including CXCR3+ CD8+ T cells), which inhibited GL261 glioma cell growth." (PMID 38104126, 2023). "Increased IP10–scFv production targeted EGFRvIII-expressing glioma cells, leading to an increased chemotactic attraction of CD8+ T lymphocytes and CXCR3+ T cells infiltrating into the tumor." (PMID 38104126, 2023). "In conclusion, our findings suggest that downregulation of the CCL2/CCR2 and CXCL10/CXCR3 axes via inhibition of the NF-κB pathway in the tumor and the tumor microenvironment might have contributed to the antitumor effects of celecoxib observed in the mouse glioma model." (PMID 32943658, 2020). "We therefore analyzed the regional distribution of CXCR3 and LRP1 by focusing on high-grade gliomas (glioblastomas, GBM)." (PMID 29146996, 2017). "Of interest, both in vitro and in vivo experiments using different glioma tumors, including GL261 cells, indicated CXCL9 and CXCL10 (which bind to their endogenous receptor CXCR3) as key ligands promoting the growth of glioma." (PMID 26157361, 2015). "A similar combination treatment of IP10–scFv fusion protein and dendritic cell–induced CD8+ cytotoxic T lymphocytes has been shown to recruit CXCR3+ CD8+ T cells, leading to cytotoxicity and apoptosis of glioma cells, thereby inhibiting glioma growth and prolonged survival." (PMID 38104126, 2023). "In GSCs, celecoxib revealed significant decrease in mRNA levels of Ccl2 and Cxcr3 but not of Ccr2 and Cxcl10, which was consistent with the high mRNA levels of Ccl2 in the glioma model and GSCs but none of Cxcl10 in GSCs." (PMID 32943658, 2020). "We newly found that in the mouse glioma model, celecoxib decreased mRNA levels of Ccl2, CxcL10 and Cxcr3 but not of Ccr2 and protein expression of CCL2 and CXCL10 in the tumor and peri-tumor." (PMID 32943658, 2020). "In our study, TREM2 knockdown significantly suppressed the expression of CXCL10 and CXCR3, which could be interpreted as anti-proliferation and anti-invasion effects of TREM2 siRNA in glioma cells." (PMID 26506595, 2016). "Glioma cell lines did not express CXCR3, CXCR4, CXCR6, CX3CR1, but high levels of CXCR7, which is a receptor for CXCL11 and CXCL12 and can mediate G-protein independent signals via arrestin." (PMID 26796342, 2016). "Here, we studied the importance of paracrine signaling in the glioma microenvironment by focusing on the celecoxib-mediated role of chemokines C–C motif ligand 2 (CCL2), C-X-C ligand 10 (CXCL10), and their receptors, CCR2 and CXCR3, in GSCs and a GSC-bearing malignant glioma model." (PMID 32943658, 2020). "Among them, one gene (CXCR5) was downregulated while five other genes (CXCR1, CXCR2, CXCR3, CXCR4, and ACKR3) were enriched in glioma compared with normal brain tissues." (PMID 35571062, 2022).
Arthritis (26 papers, 2008 to 2025). Inflammation of a joint. "The study found that the use of anti-CXCR3 monoclonal antibodies significantly reduced T cell migration and alleviated the severity of arthritis, including reductions in clinical symptoms, weight loss, and neutrophil accumulation in the joints." (PMID 40786052, 2025). "Accordingly, the expression of CXCR3 and its activation by chemokine ligands has been associated not only with numerous skin diseases but also with other disorders, such as arthritis, type 1 diabetes, and allograft rejections including the rejection of heterotopic heart allografts." (PMID 31447864, 2019). "CXCL10 KO and CXCR3 KO in mice ameliorated arthritis in CAIA model by suppressing macrophage and T cell accumulation in arthritic joints." (PMID 36860872, 2023). "By binding to CXCR3 on synovial tissue, inflammatory chemokines attract Th1 cells and macrophages, thereby contributing to arthritis accumulation." (PMID 36861127, 2023). "CXCR3 KO mice showed mild arthritis in CAIA model via the inhibition of both macrophage and T cell migration into the synovium." (PMID 36860872, 2023). "Blockade of CXCR3 has also been observed to reduce inflammatory cell infiltration and attenuate arthritis." (PMID 35924250, 2022). "Collagen-induced arthritis in DBA/1J mice has been used to study the effects of a CXCR3 antagonist on numerous markers of the cellular and humoral immune response." (PMID 34976302, 2021). "Taken together, these results demonstrate that the clinically observed amelioration of arthritis in Cxcl10–/– and Cxcr3–/– mice was reflected by suppression of joint inflammation and destruction of bone and cartilage." (PMID 28724396, 2017). "As mentioned in the introduction, the studies demonstrated that the expression of CXCL10 and CXCR3 was increased in the collagen-induced arthritis model, and neutralizing anti-CXCL10 antibodies ameliorated disease manifestation in these models." (PMID 24939012, 2014). "In rat adjuvant arthritis, blockade of CXCR3 by anti-CXCR3 mAb significantly inhibits T cell infiltration of arthritic joints and reduces the severity of arthritis." (PMID 22233170, 2012). "All these data directly demonstrate an important role of CXCR3 in the development of arthritis and CXCR3 blockade reduces the disease severity in the arthritis." (PMID 22233170, 2012). "Interestingly, in a model of arthritis, the number of T cells that express CXCR3 increases, while blocking the interactions of CXCR3 with other molecules suppresses the severity of arthritis." (PMID 35720309, 2022). "One hypothesis could be that the psoriasis patient group with a high level of CXCL10 is more prone to develop arthritis due to its chemoattractant properties on CXCR3+ CD4+ and CD8+ T cells." (PMID 34127053, 2021). "Blockade of CXCR3 has been effective in suppressing arthritis progression in murine studies." (PMID 33799480, 2021). "The TLR4 activation-induced or CXCR3-mediated CXCL10 upregulation can exert important roles in arthritis progression through TLR4 and CXCR3, suggesting that it could form a positive feedback loop between CXCL10 and its receptors TLR4 and/or CXCR3." (PMID 28724396, 2017). "Cxcl10–/– and Cxcr3–/– mice developed less severe arthritis than WT mice." (PMID 28724396, 2017). "In this study we analysed the peripheral blood components, i.e. CD14+ monocytes, CD4+, CD8+ and CD56+T lymphocytes (CD3+), CD80+, C-X-C chemokine receptor 3 (CXCR3)+, CD27+ B lymphocytes (CD19+) and CD16+CD56+CD3− NK cells, for their association with arthritis development." (PMID 27629388, 2016). "Indeed, recent studies that either targeted Cxcl10 or its receptor CXCR3 significantly ameliorated arthritis in rodents." (PMID 18706093, 2008). "Other CXCR3 antagonists, such as SCH 546738 and JN-2, also treated arthritis in CIA mice." (PMID 36860872, 2023). "Further studies have elucidated that CXCR3 plays a non-redundant role in recruiting inflammatory T cells in arthritis." (PMID 35924250, 2022).
Arthritis (continued). "OCPs from patients with arthritis had higher expression of CCR1, CCR2, CCR4, CXCR3, and CXCR4." (PMID 28619088, 2017). "There was no significant decrease in migration marker (CXCR3)+ B cells between non-converters and patients with early arthritis (p = 0.18)." (PMID 27629388, 2016). "CXCL10 is considered the most crucial and potent chemokine in CXCR3-mediated chemotaxis, as it is highly upregulated and its expression robustly correlates with disease severity in inflammatory disorders such as IBD, MS, and arthritis." (PMID 22162719, 2012). "To determine the role of CXCL10 signaling in the development of arthritis, we used the CAIA model in mice lacking Cxcl10–/– and Cxcr3–/–." (PMID 28724396, 2017).